PCNA (proliferating cell nuclear antigen)
Diseases named in the same sentence as PCNA in open-access papers (continued):
Sharing a sentence is not in itself a finding about the gene and the disease.
cervical carcinoma (continued). "In addition to its high expression in cervical cancer, PCNA is highly expressed in rapidly dividing tumour cells, which in most cases is related to poor prognosis and is an effective target for tumour treatment." (PMID 35379200, 2022). "Mechanistic studies reveal that thymic stromal lymphopoietin (TSLP) activates eosinophils that promote proliferation and survival of cervical cancer cells through upregulating Ki-67, proliferating cell nuclear antigen (PCNA) and BCL-2 and downregulating Fas and Fas ligand (FasL)." (PMID 34359674, 2021). "Overexpression of PRDX1 significantly promoted proliferation and inhibited apoptosis by increasing the expression of Nanog, proliferating cell nuclear antigen (PCNA), B-cell lymphoma-2 (Bcl-2) and downregulating the expression of Bcl2-associated X protein (BAX) in SiHa cervical cancer cells." (PMID 31956363, 2020). "We hypothesized that PRDX1 regulated the process of cervical cancer cell proliferation via upregulating the expression of Nanog and PCNA." (PMID 31956363, 2020). "A remarkably downregulated of ki67 and PCNA was found in SMYD2 depleted cervical cancer cells." (PMID 31548876, 2019). "PCNA was also found to be upregulated in cervical cancer tissues." (PMID 31319555, 2019). "BRCA1, ESR1, PCNA, and FGFR2 have already been shown to be associated with cervical cancer." (PMID 30020984, 2018). "However, the expression levels of Ki-67 and PCNA proteins in the corresponding cervical cancer tissues increased relative to those in chronic cervicitis tissues." (PMID 29051711, 2017). "However, in the corresponding chronic cervicitis tissues, the protein expression levels of Ki-67 and PCNA were both lower than those in the corresponding cervical cancer tissues." (PMID 29051711, 2017). "In addition, PCNA protein level was significantly higher in cervical cancer tissues than in the corresponding chronic cervicitis tissues (P < 0.001)." (PMID 29051711, 2017). "It has been shown in cervical cancer that inhibition of hnRNP A2/B1 inhibits cell proliferation and triggers apoptosis; additionally, in this cell line, it has been shown that knockdown of hnRNP A2/B1 markedly reduced the proliferation of these cells accompanied by a reduction in PCNA and Ki-67." (PMID 34830970, 2021). "Another wisely analyzed study has demonstrated that the predictive potential reporter biomolecules including KAT2B, PCNA, CD86, miR-192-5p, and miR-215-5p have a significant role in cervical cancer." (PMID 36723760, 2023). "In cervical cancer tissue (K14E7E2 panel), the PCNA and MCM2 stainings exhibited a nuclear pattern and were uniformly distributed throughout the thickness of the epithelium, consistent with previous reports on cervical cancer." (PMID 37626777, 2023). "We used in vitro models of cervical cancer to link these findings to replication stress responses (p-ATR, and ub-PCNA) and expression of HPV16 E7." (PMID 36266721, 2022). "Studies have shown that the expression of PCNA in cervical tissues increases with the increase in CIN and cervical cancer grade." (PMID 35379200, 2022). "Of TLS genes, increased expression of SPRTN, DTL, POLD1, PCNA, and VCP occurred most often in cervical cancers." (PMID 36266721, 2022). "The expression levels of PCNA, TDG, and LIG1 were elevated in cervical cancer group compared with the normal and CIN groups (P < 0.05)." (PMID 35379200, 2022). "Studies have shown that the expression of PCNA in cervical tissues increases with the increase in CIN and cervical cancer grade.TDG plays an important role in DNA demethylation." (PMID 35379200, 2022). "Other reports have also indicated that ATM, PCNA, and HMGB1 are highly expressed in cervical cancer tissues, and ABCG2 is expressed at low levels in cervical cancer tissues." (PMID 35379200, 2022). "The CCHE1 has demonstrated to bind and stabilize the mRNA of proliferating cell nuclear antigen (PCNA) thus promoting its over expression and increased cervical cancer cell proliferation." (PMID 32154165, 2020).
cervical carcinoma (continued). "A total of 55 cervical cancer and 40 chronic cervicitis paraffin tissues were cut into triplicate sections to analyze the expression of IFITM1, Ki-67, and PCNA proteins." (PMID 29051711, 2017). "Reduced levels of PCNA limit the effects of CCHE1 and reduce cervical cancer cell proliferation." (PMID 40005158, 2025). "Adeno-associated virus 2 requires replication protein A (RPA), replication factor C (RFC), proliferating cell nuclear antigen (PCNA), and DNA polymerase delta (POLD1) to be present for replication, and this specific combination of factors has been found to be present in cervical cancer cells." (PMID 39205238, 2024). "Expression of the cervical carcinoma expressed PCNA regulatory (CCEPR) lncRNA (also referred to as cervical carcinoma high-expressed long non-coding RNA 1; CCHE1) is highly upregulated in cervical cancers and expression correlates with tumor size and poor prognosis of cervical cancer patients." (PMID 32326624, 2020). "From this panel, the most significantly upregulated and downregulated lncRNAs are the cervical carcinoma expressed PCNA regulatory lncRNA (CCEPR) and the DNA damage-induced noncoding lncRNA (DINO), respectively." (PMID 32326624, 2020). "Interestingly, we observed that FEN1, PCNA, RAD51 and RPA1 protein levels were upregulated in cervical cancer derived cell lines as well as in keratinocytes transduced with HPV16 oncogenes when compared to normal PHK." (PMID 30674977, 2019). "Meanwhile, western blot results showed that overexpressed AFAP1-AS1 prominently elevated the expression of PCNA and enhanced the phosphorylation of MAPK and AKT, indicating that AFAP1-AS1 promoted proliferation and the relationship between AFAP1-AS1 and MAPK signal pathway in cervical cancer." (PMID 39574469, 2024). "Conversely, PRDX6 knockdown significantly inhibited tumor growth (P < 0.01), decreased PCNA protein expression, and enhanced green TUNEL fluorescence, which demonstrated that downregulation of PRDX6 suppressed the proliferation, and promoted the apoptosis of cervical cancer in vivo." (PMID 32201510, 2020). "Additionally, the xenograft model was established to evaluate whether PRDX1 affects the growth of cervical cancer in vivo, and proliferation index and apoptosis index in tumor tissues were assessed by the TdT-mediated dUTP nick end labeling (TUNEL) assay and PCNA immunohistochemical staining." (PMID 31956363, 2020). "Of the top 10 ranked upregulated genes, 2 have not been previously reported as associated with cervical cancer (NUSAP1, and CDKN3), while the other 8 have been associated with cervical cancer either scantly (SYCP2, PRC1, CCNB2 and CDC20) or widely (MKI67, CDKN2A, CDC2, and PCNA)." (PMID 23405241, 2013). "The outcomes of this assessment substantiated our preliminary observations, revealing the upregulation of RRM2 and VEGFA, alongside the downregulation of RFC4, EXO1, PCNA, TOP2A, and TYMS in cervical cancer tissues relative to normal cervical epithelial tissues." (PMID 38926832, 2024).
gastric cancer (57 papers, 1994 to 2025). A primary or metastatic malignant neoplasm involving the stomach. "Using data from the TCGA, researchers found that miR-497-5p and the expression of the cancer marker PCNA were inversely correlated in patients with stomach cancer." (PMID 38911367, 2024). "Further analysis in vitro showed that TUBA1C influenced the expression of the oncogenes: Ki-67, E2F1 and PCNA, and promote malignant progression of gastric cancer cells by affecting the cell cycle." (PMID 36941595, 2023). "Inhibition of RAD18 has also been found to suppress gastric cancer progression and sensitize gastric cancer to chemotherapy via reduction of PCNA mono-ubiquitination." (PMID 34671219, 2021). "PCNA, known as a key mediator of cell cycle and apoptosis, is involved in the development of cancers such as non-small cell lung cancer and gastric cancer, in which overexpressed PCNA acts as an oncogene." (PMID 34455417, 2021). "Consistent with clinical gastric cancer samples, Mist1 was downregulated in dysplasia and neoplasia specimens, while PCNA, a nuclear marker of proliferation, was significantly upregulated in comparison with its expression in the control group." (PMID 34149921, 2021). "Previous studies showed that higher expression of PCNA correlated with prognosis of colon adenocarcinoma, osteosarcoma, and gastric carcinoma." (PMID 33658396, 2021). "Immunohistochemistry of the gastric cancer cell line showed that the cells were derived from epithelial cells, cell proliferation was active, and staining for the proliferating cell nuclear antigen Ki-67 was ≥ 75%." (PMID 32943986, 2020). "PCNA, critical regulator in DNA synthesis, whose expression was closely related to poor prognosis of gastric cancer patients." (PMID 33209198, 2020). "Next, the results of western blot indicated that peritoneal mesothelial cells significantly increased the protein expressions of MMP3, MMP9 and PCNA in metastatic gastric cancer cells, especially peritoneal metastatic gastric cancer cells." (PMID 32139657, 2020). "Taken together, these data suggested that metastatic gastric cancer cells exhibited significant proliferative ability via increasing the expression of Cyclin D1 and PCNA." (PMID 32139657, 2020). "Meanwhile, our findings also found that the protein expression of Cyclin D1 and PCNA in metastatic gastric cancer cells were much higher than those in primary gastric cancer cells." (PMID 32139657, 2020). "Our findings were consistent with these data, suggesting that metastatic gastric cancer cells exhibited more malignant behaviors via upregulating the expression of Cyclin D1 and PCNA." (PMID 32139657, 2020). "In the TCGA database, the expression of PCNA in gastric carcinoma tissues is higher than that in normal tissues, further confirming that downregulation of PCNA levels can inhibit gastric carcinoma cells proliferation." (PMID 32368309, 2020). "Previous studies have shown statistically significant differences in PCNA expression between normal gastric mucosa and gastric carcinoma." (PMID 32368309, 2020). "The results showed that TSLL inhibited the proliferation of gastric carcinoma cells by suppressing the level of proliferating cell nuclear antigen (PCNA) and increased p21 level." (PMID 32368309, 2020). "TSLL inhibited the proliferation of gastric carcinoma cells by decreasing PCNA levels, and induced apoptosis by up-regulating the expression of Bax and down-regulating the expression of Bcl-2." (PMID 32368309, 2020). "PCNA expression is generally used as a molecular proliferation marker, which was reported to increase during progression to gastric cancer, showing a significant correlation with acute and chronic inflammation." (PMID 28662697, 2017). "A recent study has found that PCNA was expressed in 52.2 % of gastric cancer patients, and positive expression of PCNA was significantly associated with poor 3-year disease-free survival (p = 0.035)." (PMID 27806724, 2016).
gastric cancer (continued). "PCNA was expressed at significantly higher levels upon OR3A4 overexpression in gastric cancer cells, compared with control cells." (PMID 26863570, 2016). "More pronounced SLC38A1 expression in gastric cancer tissues was significantly associated with age, differentiation status, lymph node metastasis, TNM stage and PCNA (proliferating cell nuclear antigen) expression." (PMID 24712400, 2014). "In conclusion, our study showed that SLC38A1 expression was closely associated with age, differentiation status, lymph node metastasis, TNM stage and PCNA expression, as well as a worse prognosis in patients with gastric cancer." (PMID 24712400, 2014). "Seven different gastric cancer cell lines and two kinds of control cell lines were treated with antisense oligonucleotides complementary to the messenger RNA of PCNA." (PMID 7981055, 1994). "Treatment of each gastric cancer cell line with antisense oligonucleotides at concentration of 10-40 microM inhibited the cell growth, colony formation and PCNA protein production in a dose-dependent manner, but only affected normal cells slightly." (PMID 7981055, 1994). "Additionally, there is a marked accumulation of PCNA, a prognostic marker for gastric cancer, in gastric epithelial cells." (PMID 40365340, 2025). "ψ-taraxasterol (1 μM) blocks the cell cycle of gastric cancer cells at the G0/G1 phase through downregulating the expression of cyclin D1 and proliferating cell nuclear antigen (PCNA) and upregulating the expression of p21, thereby inhibiting the proliferation of HGC-27 and NCI-N87 cells." (PMID 41374059, 2025). "For eukaryotic translation initiation factor 3, subunit B (EIF3B) expression was found to be upregulated in gastric cancer tissues; it is strongly associated with proliferating cell nuclear antigen (PCNA) expression and is associated with poor outcomes in gastric cancer patients." (PMID 35008908, 2022). "Up-regulation of PCNA promotes tumor growth in gastric cancer." (PMID 33209198, 2020). "Moreover, PVT1 knockdown has been previously illustrated to result in decreased PCNA expression in gastric cancer cells which was found to inhibit cell proliferation." (PMID 31303891, 2019). "PCNA and Bax, although expressed at various steps of gastric carcinogenesis, do not show differential expression between different levels of proliferation in progression to gastric cancer." (PMID 28662697, 2017). "In addition, COX-2 expression, proliferating cell nuclear antigen (PCNA), and apoptosis-related proteins were detected, further elucidating the possible mechanism underlying the antitumor effects of UA and PTX in gastric cancer." (PMID 29190954, 2017). "The present study evaluated whether IL-8 affects the proliferation of the SGC7901 gastric cancer cell line, and investigated the effect of IL-8 on the expression levels of proliferating cell nuclear antigen (PCNA) protein and mRNA." (PMID 25364410, 2014). "In gastric cancer, the PCNA index of gastric cancer tissues with high Ep-CAM expression was higher than gastric cancer tissues with low Ep-CAM expression, indicating that Ep-CAM might be associated with the proliferative activity of cancer cells." (PMID 20461151, 2010). "In conclusion, both MVC and PCNA LI may be good prognostic indicators in patients with gastric carcinoma." (PMID 7543771, 1995). "PCNA expression level is related to the malignancy of gastric cancer cells." (PMID 7981055, 1994). "In addition, polysaccharides also inhibit 1-methyl-2-nitro-1-nitrosoguanidine-induced precancerous lesions in gastric cancer rats by downregulating the gene expression of Wnt2β, Gsk3β, PCNA, CyclinD1, and β-catenin by inhibiting the Wnt/β-catenin signaling pathway." (PMID 36144560, 2022).
gastric cancer (continued). "This may be associated with the IL-8 regulatory mechanism of PCNA expression, however, this regulatory effect does not appear to be involved in gastric cancer cell proliferation." (PMID 25364410, 2014). "Results in the present study showed that knockdown of AQP-1 decreased protein expression of PCNA and MCM2 in gastric cancer cells, suggesting the anti-proliferative role of AQP-1 silence in gastric cancer." (PMID 33209198, 2020). "Our previous studies have demonstrated that harmine can down-regulate PCNA and COX-2 expression in human gastric cancer cells." (PMID 32364228, 2020). "Subsequently, Xu and colleagues demonstrated that the knockdown of RAGE reduced GC cell proliferation and invasion of gastric cancer, decreased expression of AKT, PCNA and MMP-2, and induced cell apoptosis and cycle arrest." (PMID 25860956, 2015). "In conclusion, the NF-κB p65 inhibitor, SN50, inhibited the invasiveness of the gastric cancer cells by downregulating the protein expression of MMP-9, PCNA and VEGF and upregulating the protein expression of TIMP-1." (PMID 24137341, 2013). "A total of 108 specimens resected from patients with gastric carcinoma were investigated by staining with monoclonal antibodies against F-VIII RA and PCNA." (PMID 7543771, 1995). "PCNA and MMP are closely related to the occurrence and metastasis of gastric cancer." (PMID 34091587, 2021). "In addition, myrrh inhibited the expression of PCNA, COX-2, and Bcl-2 as well as increased Bax expression in gastric cancer cells." (PMID 32364228, 2020). "In conclusion, the present study demonstrated that IL-8 exerts no direct effect on the proliferation of gastric cancer cells, but influences the expression levels of PCNA protein and mRNA, depending on the IL-8 dosage." (PMID 25364410, 2014). "We found a close relationship between pRB expression and PCNA in non-neoplastic mucosas as well as in gastric carcinomas." (PMID 7947078, 1994). "Dihydroartemisin downregulated PCNA and MMP-2, mediated by p16-Cyclin D1/CDK4-Rb pathway, suppresses the cell growth and metastasis of human gastric cancer (GC) cells." (PMID 39161904, 2024). "TUBA1C was proved to be a direct target of EGFR-AS1, and TUBA1C promotes gastric cancer proliferation, migration and invasion by accelerating the progression of the cell cycle from the G1 phase to the S phase and activating the expression of oncogenes: Ki-67, E2F1 and PCNA." (PMID 36941595, 2023). "In the same way, we found that COL4A1 silence downregulated the expressions of Ki67, PCNA, MMP2, MMP9, N-cadherin and Vimentin but promoted E-cadherin expression in MKN-45 cells, revealing that COL4A1 silence could help to suppress the proliferation, metastasis and EMT in gastric cancer." (PMID 35297303, 2022).